KRAS (KRas proto-oncogene, GTPase)
Diseases named in the same sentence as KRAS in open-access papers (continued):
Sharing a sentence is not in itself a finding about the gene and the disease.
tumor (continued). "KRAS mutation induced the silencing of MATE1 (multidrug and toxic compound extrusion 1), a pump responsible for the efflux of metformin from the tumor cells, through the upregulation of DNMT1." (PMID 34074330, 2021). "The current study have revealed that high levels of F. nucleatum were related with key tumor molecular features of CRC, including MSI-high and KRAS mutation which have been associated with clinical outcome in advanced CRC." (PMID 33613745, 2021). "Subgroup analysis of clinical trials showed that the efficacy of tumor immunotherapy was better in the KRAS group than in the EGFR group." (PMID 34136375, 2021). "Exploring new avenues for TBK1 targeted therapy in PDAC have shown that Compound II can reduce viability in human PDAC cell lines and reduced tumor burden in a pre-clinical model of KRAS driven PDAC (p48-Cre; LSL-KrasG12D; Cdkn2alox/lox, KIC)." (PMID 34572737, 2021). "We show that CCT3833 inhibits RAF and SRC in KRAS-mutant tumors in vitro and in vivo, and that it inhibits tumor growth at well-tolerated doses in mice." (PMID 33130216, 2021). "We further tested the effects of KRAS-Mφ on tumor progression in the orthotopic xenograft tumor models." (PMID 33833221, 2021). "Using patient-derived xenograft models, the response and tumor inhibition of RGS were significantly higher in the KRAS-mutant subgroup, while p-MEK, p-ERK, and p-AKT levels of RGS-treated tumors were significantly decreased." (PMID 34347396, 2021). "Together with the increased presence of endothelium in the tumour, the detection of pericytes points to normalisation of the vasculature of the tumour as a result of KRAS G12C inhibition." (PMID 34625563, 2021). "Using genetically engineered murine models (GEMM) and tumor‐fibroblast co‐cultures, we show that KRAS‐mt epithelial cancer cells downregulate the expression of ECM‐related genes in the neighboring fibroblasts." (PMID 33817986, 2021). "A 2’-4’ constrained ethyl (cEt)-modified molecule, AZD4785, has good potency with high delivery efficiency and potent KRAS knockdown in tumor tissues." (PMID 34301278, 2021). "They found heterogeneity and heterozygosity in KRAS status among the CTCs within a patient and between CTCs and tumor tissues." (PMID 34798902, 2021). "Galectin-3–induced αvβ3 integrin clustering drives KRAS addiction in tumor cells, and galectin-3 inhibition represents an actionable target to treat KRAS G12D-bearing cancers." (PMID 34131655, 2021). "In this study, we take advantage of the finding to develop small molecule inhibitors that stabilize the “open conformation” of activated KRas in tumor cell, thus preventing KRas from converting to its signaling one." (PMID 35069209, 2021). "The KRAS G12C inhibition group (30 mg kg‐1 AMG510) showed persistent tumor growth in these experiments, highlighting the impact of the drug resistance to AMG510 of the CO‐04‐0070 model." (PMID 34151545, 2021). "We found that co-injection of KRAS-Mφ markedly enhanced tumor growth, as shown by tumor size and weight." (PMID 33833221, 2021). "Our results also suggest that high F. nucleatum levels are correlated with tumor growth, distant metastasis, poor differentiation, MSI-high, and KRAS mutation in CRC." (PMID 33613745, 2021). "Physicians were also questioned about the impact of tumor sidedness on their first-line targeted therapy choice for patients with KRAS wildtype." (PMID 34199694, 2021). "Overall, the results indicate that the immune system suppresses tumor-forming capacity of KRAS KO cell lines by several hundredfold (>300) compared to that in nude mice." (PMID 33674596, 2021).
tumor (continued). "Studies implicate that CRAF is vital for mutant KRAS signal transduction and tumor initiation other than BRAF." (PMID 34301278, 2021). "The TAMs in KRAS KO tumors were skewed toward M1 polarization, while tumor-infiltrating lymphocytes (TILs) were dominated by CD8 cytotoxic T cells (40%) and natural killer T (NKT) cells (40%), compared to CD4 helper T cells (20%)." (PMID 33674596, 2021). "Numerous downstream effectors of EGFR signaling bypassing activated KRAS and promoting tumor progression have been identified, including NFATc1 and c-MYC." (PMID 34070180, 2021). "Several studies have also indicated that after MEK inhibition, KRAS-mutant tumours are more dependent on autophagy and that co-targeting MEK and autophagy results in a synergistic response." (PMID 34200676, 2021). "They observed tumor formation similar to nude mice, leading to the conclusion that the immune system suppressed tumor formation in KRAS KO mice." (PMID 34781949, 2021). "We further assume that, because the oncogenic pathways responsible for the initiation and propagation of tumors vary markedly from one tumor subtype to another, KRAS mutant CRC cells upregulate specific sets of AATs to support growth and proliferation." (PMID 34003553, 2021). "The mutations of several genes in different tumor settings such as NRF2 (nuclear factor erythroid 2-related factor 2), KEAP1 (kelch-like ECH-associated protein 1), and KRAS, have been identified as radiosensitising or radioresistant factors." (PMID 36046142, 2021). "Subsequently, Compound 17f, the most promising PDEδ degrader, shows enhanced anti-tumor activity in the KRAS-mutant CRC cell line and its xenograft model." (PMID 34742312, 2021). "KRAS encodes a member of the RAS family of small GTPases and activating mutations in RAS can cause uncontrolled cell proliferation and tumor formation." (PMID 33435376, 2021). "Third-line lorlatinib showed limited efficacy but chemoimmunotherapy resulted in disappearance of the KRAS mutant clone and clinical tumor control for another eight months." (PMID 34548910, 2021). "Another pre-clinical study using AZD4785 on a panel of various tumor cell lines including CRC showed potent downregulation of mutant KRAS." (PMID 34944853, 2021). "Recent works have established two different groups of KRAS mt NSCLC: KRAS-dependent or KRAS-independent, according to their requirement for mutant KRAS to maintain tumor viability." (PMID 35083149, 2021). "KRAS signaling modulates a plethora of hallmark tumor pathways, including PDAC tumor initiation, maintenance, desmoplasia, metastasis, immunity, and drug sensitivity." (PMID 34947972, 2021). "Conversely, PLEXIND1 acts as a tumor suppressor in the PDAC cell line (BxPC-3) with wild-type KRAS (KRASwt), as its reduced expression results in higher cell viability (in-vitro) and tumor growth (in vivo)." (PMID 34439202, 2021). "The translational potential of this combination is strengthened by the growing identification of oncogenic mutations in HRAS, KRAS (HGNC IDs 5173, 6407), NRAS and BRAF (HGNC ID 1097) genes in SS cell lines and clinical tumor subsets." (PMID 34857011, 2021). "KRAS activation in cancer cells induces the expression and secretion of proinflammatory cytokines, stimulating the recruitment of neutrophils to the tumor." (PMID 33802006, 2021). "On average, tumour mutational burden (TMB) was 18 mutations/Mb and 34.4%, 31.3% and 25.7% of patients had structural or copy number mutations in KRAS, BRAF and NRAS, respectively." (PMID 34600575, 2021).
tumor (continued). "The metabolic reprogramming in tumor cells by oncogenes, like RAS and, in particular, the mutant KRAS, supports the uncontrolled tumor growth, promotes the Warburg effect and affects the glutamine/lipid metabolism, thereby mediating the therapy resistance." (PMID 34359663, 2021). "We also looked at the sensitivity of tumor cells with WT KRAS to treatment with Indisulam, and demonstrated that KRAS4A was downregulated in response to both Indisulam and knockdown of RBM39 in H1650 cells." (PMID 34257283, 2021). "During carcinogenesis, the activation of KRAS proteins triggers tumor initiation and accelerates tumor growth." (PMID 34440178, 2021). "Consistently, increased Ccl2 promoted macrophage recruitment into the TME and enabled tumour recurrence following oncogenic KRAS extinction." (PMID 33671588, 2021). "For stage II/III CRC, univariate logistic regression analysis showed that histology type, tumor location, degree of differentiation, and CEA and CA19-9 levels were significantly correlated with KRAS mutations." (PMID 34221952, 2021). "Moreover, it has been reported that the extent of optimal tumor-free margin may vary according to the KRAS mutation status, with 1–4 mm margins being considered sufficient in patients with wild-type KRAS, whereas 1-cm margins being considered insufficient for those with mutant KRAS status." (PMID 33858364, 2021). "KRAS mutation has been reported to increase vascular endothelial growth factor (VEGF) expression and to promote the construction of a tumour vascular network." (PMID 34525976, 2021). "Another recent study published a similar finding of the response of a KRAS A59T-harboring tumor to cetuximab, with the additional observation that this variant was enriched in tumors with low mutant allele frequencies." (PMID 34063999, 2021). "Other surveys of both KRAS-mutated and HRAS-mutated patient tumor samples have found similar results." (PMID 33924994, 2021). "A miR-34a-expressing DNA vector encapsulated in liposomal nanoparticles (nanovector) is effective at reducing tumor growth in subcutaneous and orthotopic xenograft models, and more so than similar nanovector strategy with KRAS-targeting miR-143 and miR-145." (PMID 34591242, 2021). "KRAS mutants in CRC play a role via hypoxia to enhance the accessibility of nutrients for cancer cells (tumor) by creating new vessels." (PMID 33691728, 2021). "Then, they showed that cetuximab-based BiTE antibody mediated potent redirected lysis of KRAS- and BRAF-mutated CRC lines in vitro and prevented the growth of tumours from xenografts." (PMID 34663410, 2021). "The dependence on KRAS for tumor growth/survival is reduced in the majority of cell lines that we screened, and is instead manifested in the suppression of antitumor immunity." (PMID 33674596, 2021). "Leukemia inhibitory factor (LIF), a cytokine secreted by stromal myofibroblasts and tumor cells, has recently been highlighted to promote tumor progression in pancreatic and other cancers through KRAS-driven cell signaling." (PMID 33846527, 2021). "Sixty-four patients (59.8%) were KRAS wild-type in both primary tumor and CRLM and 26 (24.3%) were KRAS mutated in both primary tumor and CRLM." (PMID 33946899, 2021).
tumor (continued). "KRAS activates essential pathways to control the expression and secretion of cytokines and chemokines from tumor cells, thereby regulating the recruitment and development of immune cells." (PMID 34290984, 2021). "KRAS oncogenic signaling is responsible for modulation of tumor microenvironment, with translation factors being among the most prominent deregulated targets." (PMID 33672357, 2021). "A very high concordance rate between tumor tissue und detected cfDNA KRAS SNVs further validates our approach." (PMID 33430810, 2021). "KRAS and NRAS mutation were detected in 39.5% (83/210) of tumor cases examined, of which 36.7% (77/210) and 2.9% (6/210) were occurred in KRAS and NRAS gene respectively." (PMID 33784337, 2021). "In contrast, all of the 5 mice (100%) injected with SW48 cells mixed with KRAS-Mφ or siMOCK-Mφ exhibited orthotopic tumor formation, with larger tumor sizes." (PMID 33833221, 2021). "A salient feature that distinguishes PDAC from other KRAS-mutant cancers such as lung and colon cancers is its extensive fibro-inflammatory stroma, which typically accounts for 80–85% of the tumor bulk." (PMID 34771644, 2021). "Oncogenic activation of KRAS and its surrogates is essential for tumour cell proliferation and survival, as well as for the development of protumourigenic microenvironments." (PMID 34381028, 2021). "MRTX849 demonstrated pronounced tumour regression and objective responses in patients with KRAS G12C positive colon adenocarcinomas." (PMID 33669775, 2021). "KRAS‐amplified tumor cells show insensitivity to MAPK blockade as they can adaptively respond by mobilization of their reserve inactive KRAS to increase KRAS‐GTP state." (PMID 33532680, 2021). "The study identified an unmet need to develop therapeutic approaches to target distinct tumor subpopulations within heterogeneous KRAS-mutant lung tumor to achieve a robust therapeutic response." (PMID 34309585, 2021). "Small nucleolar RNA SNORD50A and SNORD50B (SNORD50A/B) has been reported to be recurrently deleted and function as a putative tumor suppressor in different types of cancer by binding to and suppressing the activity of the KRAS oncoproteins." (PMID 33742136, 2021). "In our previous work, KRAS mutant-specific knockdown using short hairpin RNA vectors targeting KRAS G12C or KRAS G12V significantly but incompletely suppressed tumor growth in four NSCLC cell lines, all of which retained the wild-type KRAS allele." (PMID 34885068, 2021). "Another problem is the heterogeneity of mutations in primary tumours and metastatic lesions, especially EGFR and KRAS, with the misclassification rate ranging from 0 to 45%." (PMID 33602172, 2021). "Oncogenic KRAS is known to regulate metabolism in the tumor environment increasing glucose uptake and glycolysis by directly regulating HK1 activity and increasing LDHA expression." (PMID 34120142, 2021). "We demonstrate that at an advanced tumor stage, dependence on KRAS for tumor growth is reduced and is manifested in the suppression of antitumor immunity." (PMID 33674596, 2021). "We also recently demonstrated that the constitutive expression of oncogenic KRAS persistently upholds the mesenchymal characteristics of claudin-low tumor cells." (PMID 34675248, 2021). "Tumor biopsies were examined as wild-type KRAS (exon 2, 3, 4), NRAS (exon 2, 3, 4) and BRAF V600E for all patients included in this study." (PMID 34335943, 2021). "KRAS and BRAF mutation status in plasma cfDNA are highly correlated with mutation status in tumor tissue." (PMID 34070592, 2021).
tumor (continued). "Loss of Sik1 and Sik3 in the SIK subfamily, resulted in intensified tumor growth in in vivo models of KRAS-driven NSCLC." (PMID 34781949, 2021). "Wild-type KRAS has been shown to act as a tumor suppressor gene during the differentiation of myeloid cells and inhibit lung carcinogenesis in murine teratomas." (PMID 33982211, 2021). "Most notably, inactivation of SMAD4 accelerated KRAS KO tumor development in mice in a statistically significant manner and fully restored the epithelial phenotype of KRAS KO tumors." (PMID 33674596, 2021). "In the mouse model of PDAC, SMO-independent GLI1 activation promotes transformation and requires both TGFβ and KRAS signaling where inhibition of TGFβ by TbRI antagonist SD208 significantly reduces tumor burden and increases infiltration of lymphocytes." (PMID 34113570, 2021). "Subcutaneous xenograft tumor models were used to confirm the differential activity of RGS in SW48 (RAS wild-type) and DLD1 (KRAS G13D mutation) in vivo, and tumor-bearing nude mice were randomly assigned to receive PBS or RGS." (PMID 34347396, 2021). "They showed that glycolysis is increased in autophagy-competent cells versus autophagy-deficient cells harbouring KRAS mutations and that this process facilitated RAS-mediated adhesion-independent transformation in RAS-driven tumor growth." (PMID 33691728, 2021). "KRAS status was determined by whole exome sequencing (WES) of tumor tissue in 301 patients with LUAD of the 1274 randomized participants with NSCLC, being 69/301 (22.9%) KRAS mt LUAD." (PMID 35083149, 2021). "When comparing SGC frequency, the Ela-Cre-ERT-LGL KRAS model of SDC has the advantage of having a 100% frequency of tumor induction." (PMID 33990543, 2021). "The concordance rates of the tumor tissue or the metastatic lymph node versus plasma of KRAS results were 78.9% (56/71) and 70.4% (19/27), respectively, which were not statistically significant (κ = 0.059, p = 0.410; κ = 0.033, p = 0.547, respectively)." (PMID 33915745, 2021). "Mutant KRAS induces Tregs via secretion of IL-10 and transforming growth factor-β1 from tumor cells." (PMID 34885068, 2021). "To define the spectrum of mutations in the KRAS gene in the Saudi population, we checked mutations in 80 CRC tumor tissues." (PMID 34369256, 2021). "In light of our above findings, we subsequently explored the biological functions of KRAS-reprogrammed macrophages (KRAS-Mφ) in tumor progression." (PMID 33833221, 2021). "Up until now, the association between all RAS status (exon 2, 3 and 4 of KRAS and NRAS genes) and tumor features has been investigated by few studies." (PMID 33784337, 2021). "KRAS, NRAS, and BRAF mutations in PDTOs were matched to 86.6%, 100%, and 100% of those in corresponding tumor tissues, respectively." (PMID 34359661, 2021). "For example, co-targeting of anti-apoptotic proteins BCL-XL or MCL-1 and MEK promotes tumor regression in KRAS-mutant tumor models compared with MEK targeting alone." (PMID 34301278, 2021). "Receptor tyrosine kinase (RTK) coexpression facilitates tumor resistance due to redundancies in the phosphatidylinositol-3′-kinase/protein kinase B and KRAS/extracellular-signal–regulated kinase signaling pathways, among others." (PMID 32646879, 2021). "The cell-intrinsic mechanisms by which KRAS performs key functions in various aspects of tumor biology are well-documented." (PMID 33833221, 2021). "SHOC2 inhibitor cooperated with MEK inhibitor or EGFR-TKI impairs cell proliferation and viability in KRAS- or EGFR mutant driven tumor cells." (PMID 34102455, 2021).